ENSG00000255330 (novel  protein)
Gene: Protein-coding gene on chromosome 6 (127,438,406 to 127,519,001, reverse strand). Ensembl gene ENSG00000255330.
Genetic constraint (gnomAD): Missense variants: 1,116 observed, 1,180.7 expected, observed/expected ratio (o/e) 0.95, 90% interval 0.9 to 0.99. Synonymous variants: 570 observed, 514.83 expected, observed/expected ratio (o/e) 1.11, 90% interval 1.03 to 1.19.